FUBP1 (far upstream element binding protein 1)
Diseases named in the same sentence as FUBP1 in open-access papers (continued):
Sharing a sentence is not in itself a finding about the gene and the disease.
glioma (50 papers, 2012 to 2025). A benign or malignant brain and spinal cord tumor that arises from glial cells (astrocytes, oligodendrocytes, ependymal cells). "FUBP1 mutation was found in most of the cancer types analyzed in TCGA, especially in glioma, melanoma, and uterine corpus endometrial carcinoma." (PMID 35274005, 2022). "It was reported that almost every glioma with a CIC or FUBP1 mutation exhibited an IDH gene mutation." (PMID 32676453, 2020). "In human gliomas, FUBP1 levels were positively correlated with the pathologic stage, the high levels of FUBP1 expression were associated with shorter survival." (PMID 28076379, 2017). "This was inconsistent with the past research whereby FUBP1 was shown to be associated with poor prognosis in glioma patients." (PMID 29371945, 2017). "The mutational analysis of 363 brain tumors reported the distribution of ATRX, CIC (homolog of the Drosophila capicua gene), and FUBP1 mutations in gliomas." (PMID 24202337, 2013). "Accordingly, there was a concurrence in the incidence of CIC and FUBP1 mutations in the TCGA cohort of low grade gliomas (odds-ratio 3.79; Fisher exact test p-value = 0.0006)." (PMID 24086756, 2013). "Mutations in the critical chromatin modifier ATRX and mutations in CIC and FUBP1, which are potent regulators of cell growth, have been discovered in specific subtypes of gliomas, the most common type of primary malignant brain tumors." (PMID 22869205, 2012). "Almost every glioma with a CIC or an FUBP1 mutation exhibited loss of both chromosomes 1p and 19q (98%, n=36)." (PMID 22869205, 2012). "The mutational analysis of 363 brain tumors reported here represents the largest effort to date to define the distribution of ATRX, CIC, and FUBP1 mutations in gliomas." (PMID 22869205, 2012). "Every glioma with a CIC or an FUBP1 mutation exhibited an IDH gene mutation." (PMID 22869205, 2012). "Prior studies have demonstrated that in low‐grade IDH‐mutant gliomas, TERTp mutation is associated with genetic alterations in CIC, FUBP1, and MYC, as these genes are closely related to 1p/19q deletion." (PMID 39804195, 2025). "Genes with synergistic relationship with IDH1 mutations in glioma such as ATRX have been previously reported, representing a glioma subgroup distinct from those with co-mutations of IDH1 with CIC and FUBP1 mutations." (PMID 39160568, 2024). "EGFR (21%), PTEN (17%), and NF1 (12%) mutations in the high-glioma risk score group and CIC (28%), FUBP1 (11%), and NOTCH1 (10%) mutations in the low-risk score group were identified, and the mutation frequency of these genes was greater than 10%." (PMID 36311792, 2022). "The existence and function of FUBP1 in cancer have been reported for neuroblastoma, myeloid leukemia, tongue squamous cell carcinoma, glioma, etc.." (PMID 35274005, 2022). "Some studies have shown that increased expression of FUBP1 is a predictor of poor survival in human glioma." (PMID 35413821, 2022). "CIC and FUBP1 mutations occur probably because of the unbalanced translocation and often emerge after IDH mutation and 1p/19q codeletion in gliomas." (PMID 35592520, 2022). "LowRisk_IDH1mut/ATRXwt group, consisted of O largely, enriched almost all gliomas with 1p/19q codeletion, CIC mutation, and FUBP1 mutation." (PMID 34093830, 2021). "For example, there is a positive correlation between the expression of FUBP1 and c-MYC in glioma and high expressions of FBP1 and c-MYC are associated with poor prognosis." (PMID 34116677, 2021).
glioma (continued). "The latest evaluation of molecular subgroups of gliomas identified ATRX, CIC, and FUBP1 mutations, and allowed distinguishing patients with IDH1/CIC/FUBP1 or IDH1/ATRX mutations." (PMID 27834917, 2016). "This analysis uncovered frequent alterations in ATRX, CIC, and FUBP1 in new glioma subtypes and identified an association between ATRX alterations and ALT in grade II-III gliomas." (PMID 22869205, 2012). "In addition to expanding on previous preliminary reports of the frequency of ATRX, CIC, and FUBP1 mutations in selected tumor types, our study for the first time identifies associations between these mutations and age at diagnosis and clinical outcome among glioma patients." (PMID 22869205, 2012). "Additionally, tumor treating fields (TTF) -mediated downregulation of circMMD can inhibit glioma progression by the FUBP1/FIR/DVL1 and miR-15b-5p/FZD6 pathways." (PMID 37723588, 2023). "FUBP1 level was found correlated with pathological stage and survival in glioma patients." (PMID 33954195, 2021). "The resulting three categories were as follows: I-A (IDH1/ATRX mutation), I-CF (IDH1/CIC/FUBP1 mutation), and I-X gliomas (not I-A or I-CF)." (PMID 29026176, 2017). "No reports have elucidated the function of FUBP1 mutation in gliomas." (PMID 35592520, 2022). "Additionally, in glioma, FUBP1 effectively facilitates the proliferation of glioma cells, and its mechanism may be related to c-Myc." (PMID 35546072, 2022). "Importantly, IDH mutated, 1p/19q codeleted gliomas were characterized by mutations in CIC, FUBP1, NOTCH1, and TERT promoter, suggesting these mutations could serve as oligodendroglial lineage markers." (PMID 27556304, 2016). "Alterations in CDK4/6, CIC, FGFR2/3/4, FUBP1, KIT, MET, NF1, PEG3, RB1, and NTRK2 were additional factors correlated with the survival of different subtypes of gliomas." (PMID 36998447, 2023). "The remaining 18% (14/80) were reclassified as glioma (NOS) given their IDH1/2 WT, CIC WT, and FUBP1 WT status." (PMID 33778493, 2021). "The most commonly recurrent deletion events on chromosome 1p (ARID1A, CDKN2C, FUBP1) and chromosome 19q (CIC) were observed in gliomas of CYT-low cohort." (PMID 31428092, 2019). "This analysis defined two highly recurrent genetic signatures in gliomas: IDH1/ATRX (I-A) and IDH1/CIC/FUBP1 (I-CF)." (PMID 24202337, 2013). "This analysis allowed us to define two highly recurrent genetic signatures in gliomas: IDH1/ATRX (I-A) and IDH1/CIC/FUBP1 (I-CF)." (PMID 22869205, 2012). "Increasing evidence suggests that FUBP1 is overexpressed in a variety of malignancies, including prostate cancer, bladder cancer, liver cancer, colon cancer, breast cancer, non-small-cell lung cancer (NSCLC), glioma, and gastric cancer." (PMID 28076379, 2017).
breast carcinoma (14 papers, 2013 to 2025). "CCNJ and FUBP1 are essential for the growth of HER2+ breast cancer cells and FUBP1, a transcription factor regulating transcription and translation of various genes including c-Myc." (PMID 38088952, 2024). "Regarding the phosphorylation of FUBP1, significant elevation was found in breast cancer at Y126 and T174, in UCEC at T153 and S630, in lung adenocarcinoma at S120, and in clear cell RCC at S120 based on the CPTAC datasets." (PMID 35274005, 2022). "Immunohistochemical staining was used to detect the expression level of FUBP1 in breast cancer, ovarian cancer, colon cancer, clear cell RCC, UCEC, lung adenocarcinoma and normal control tissues." (PMID 35274005, 2022). "Whereas, overexpression of FUBP1 is also often appears in various cancers including breast cancer, gastric cancer, hepatocellular carcinoma, nasopharyngeal carcinoma and leukemia." (PMID 34116677, 2021). "A previous study showed that miR-16 played a role in anti-tumour apoptosis in breast cancer and gastric cancer by downregulating FUBP1." (PMID 31511046, 2019). "We previously reported that circACTN4 could bind with FUBP1 to promote tumorigenesis and the development of breast cancer (BC) by increasing the expression of MYC." (PMID 40612865, 2025). "Additionally, circACTN4, potentially mediated by USF2, interacts with FUBP1 to facilitate breast cancer progression by upregulating MYC expression." (PMID 39430741, 2024). "Our findings uncover a pivotal mechanism that circACTN4 mediated by USF2 might interact with FUBP1 to promote the occurrence and development of breast cancer via enhancing the expression of MYC." (PMID 34116677, 2021). "The far upstream element binding protein 1 (FUBP1), also known as helicase V, is highly expressed in various tumour tissues and cell lines, including liver cancer, squamous cell carcinoma, renal cell carcinoma, breast cancer, prostate cancer, bladder cancer and non-small lung cancer." (PMID 31511046, 2019). "The study have shown that the expressions of FUBP1 and its target MYC in breast cancer tissues were higher than those in adjacent normal tissues." (PMID 34116677, 2021). "Previous studies have reported that FUBP1 protein can regulate c-MYC transcription by binding to the c-MYC far-upstream element (FUSE) sequence, thereby affecting tumor metastasis in lung cancer and breast cancer." (PMID 38443680, 2024). "Moreover, the noncoding RNAs LCAT3 and circACTN4 can interact with FUBP1 and thereby activate c-MYC in lung cancer and breast cancer respectively." (PMID 35274005, 2022). "Further mechanistic research revealed that circACTN4 could competitively bind to FUBP1 and block the binding of FUBP1 with FIR, thus promoting the transcription of MYC and development of breast cancer." (PMID 34116677, 2021). "Additionally, FUBP1 can be competitively bound by circACTN4, resulting in reduced FIR-binding and subsequently triggering the activation of c-MYC transcription, which leads to the progression of breast cancer." (PMID 38443680, 2024). "Further mechanistic research proved that circACTN4 could competitively bind to far upstream element binding protein 1 (FUBP1) to prevent the combination between FUBP1 and FIR, thereby activating MYC transcription and facilitating tumor progression of breast cancer." (PMID 34116677, 2021).
hepatocellular carcinoma (11 papers, 2013 to 2025). A malignant tumor that arises from hepatocytes. "In contrast, in other tumors, including hepatocellular carcinoma and ovarian cancer, the more general genomic alteration of FUBP1 is excessive expression, which is often inversely correlated with overall survival." (PMID 33987449, 2021). "The oncoprotein role of FUBP1 and overexpression of FUBP1 have been demonstrated in multiple types of cancers, such as hepatocellular carcinoma, neuroblastoma, myeloid leukemia, and endometrial cancer." (PMID 33987449, 2021). "Increasing evidence has demonstrated the oncogenic role of Fubp1 and deregulated expression of FUBP1 has been reported in several types of tumors, including hepatocellular carcinoma, nasopharyngeal carcinoma, gastric cancer, leukemia and neuroblastoma." (PMID 32481602, 2020). "We and others found FUBP1 to be upregulated in a number of tumor entities, such as hepatocellular carcinoma (HCC), prostate, and colorectal cancer." (PMID 28588622, 2017). "For example, FUBP1 is strongly overexpressed in human hepatocellular carcinoma and is necessary for resistance to apoptotic stimuli and cell proliferation by direct or indirect repression of cell cycle inhibitors and proapoptotic target genes." (PMID 28076379, 2017). "Highly expressed FUBP1 was negatively correlated with survival rate of patients with hepatocellular carcinoma (HCC) and could promote the proliferation of HCC cells." (PMID 33954195, 2021). "Additionally, inhibiting far upstream element binding protein 1 (FBP1) has been shown to increase hepatocellular carcinoma (HCC) sensitivity towards apoptotic stimulation, which therefore inhibits cell proliferation." (PMID 23946791, 2013). "FUBP1 knockdown in human hepatocellular carcinoma (HCC) cell lines also decreases proliferation, and impairs tumour formation in mouse xenograft models." (PMID 28398229, 2017).
lung carcinoma (11 papers, 2019 to 2024). "We found that both mRNA and protein levels of FUBP1 were significantly upregulated in LUAD, and the high expression of FUBP1 was associated with shorter survival time in lung cancer patients." (PMID 34274028, 2021). "In discordance with these expression patterns of FUBP1, however, survival analysis showed that high expression of FUBP1 was associated with poor overall survival (OS) in lung cancer patients." (PMID 32481602, 2020). "The genes Fubp1, Cox6b1, Pon3, Iars2, Ctsd, and Akr1b1 have been previously shown to promote lung cancer proliferation." (PMID 39273313, 2024). "On the other hand, elevated expression of FUBP1 was reported to promote progression of lung cancer, possibly by regulating c-Myc expression and alterative splicing." (PMID 39146021, 2024). "Our study revealed that FUBP1 acts as an oncoprotein in lung cancer, which promotes the G1 to S phase (G1/S) transition and cell proliferation." (PMID 34274028, 2021). "Upon FUBP1 knockdown, we observed a significant inhibition of growth and colony survival of lung cancer cells." (PMID 34274028, 2021). "Collectively, FUBP1 also plays an oncogenic role by enhancing malignant phenotypes of lung cancer cells." (PMID 34274028, 2021). "To assess the cellular mechanism of Fubp1 in lung cancer, we utilized Lewis lung carcinoma (LLC) cells." (PMID 32481602, 2020). "This study highlighted the genetic heterogeneity across histological subtypes of lung cancer and reported novel loci for lung cancer at 1p31.1 (rs71658797, FUBP1), 6q27 (rs6920364, RNASET2), 8p21.1 (rs11780471, CHRNA2), and 15q21.1 (rs66759488, SEMA6D)." (PMID 31069257, 2019). "For example, LCAT3 plays an oncogenic role in lung cancer by binding to FUBP1 to activate MYC." (PMID 36482116, 2022). "Furthermore, like LCAT3 knockdown, FUBP1 knockdown also suppressed the migration of A549 and Calu1 lung cancer cells, and triggered G1 arrest by significantly reducing the levels of cyclin A2 and cyclin D1." (PMID 34274028, 2021). "Indeed, the ChIP assay showed that FUBP1 bound to the c-MYC promoter in lung cancer cells, which is significantly reduced upon LCAT3 knockdown." (PMID 34274028, 2021). "Taken together, FUBP1 might exhibit heterogeneous and complicated functions in lung cancer development." (PMID 32481602, 2020). "Overexpressed LCAT3 then recruit FUBP1 to c-MYC promoter to transactivate c-MYC expression, leading to enhanced proliferation, survival, migration/invasion and metastasis of lung cancer cells." (PMID 34274028, 2021). "Gene profiling analysis in A549 lung cancer cells after treatment with anti-cancer chemotherapeutic drugs, alisertib and etoposide, (GEO accession: GSE102639) showed that Fubp1 expression was significantly reduced by these anti-cancer drugs." (PMID 32481602, 2020). "For example, FUBP1 can be recruited to c-MYC FUSE through lncRNA binding, resulting in the activation of c-MYC transcription and facilitating the proliferation, survival, invasion, and metastasis of lung cancer cells." (PMID 38443680, 2024). "Mechanistically, LCAT3 recruited Far Upstream Element Binding Protein 1 (FUBP1) to the MYC far-upstream element (FUSE) sequence, thereby activating MYC transcription to promote proliferation, survival, invasion and metastasis of lung cancer cells." (PMID 34274028, 2021). "Finally, we analyzed the effect of LCAT3 and FUBP1 on several cell cycle regulatory genes, known to be MYC targets in lung cancer cells." (PMID 34274028, 2021). "In addition, it was shown that lung cancer associated transcript 3 (LCAT3), a new m6A-regulated lncRNA, can bind to Far Upstream Element Binding Protein 1 (FUBP1) activating MYC transcription and promoting lung cancer cell proliferation, invasion and metastasis." (PMID 35547245, 2022). "To investigate whether a cross-talk exists between LCAT3 and FUBP1, we first assessed FUBP1 levels in LCAT3-silenced lung cancer cells and found no change." (PMID 34274028, 2021).
lung carcinoma (continued). "However, interestingly, gene profiling analysis comparing lung cancer and adjacent normal cell (GEO accession: GSE118370) revealed that FUBP1 expression was significantly downregulated in lung adenocarcinoma, the most common lung cancer subtype among non-smokers and women." (PMID 32481602, 2020). "When we analyzed FUBP1 expression during lung cancer progression (GEO accession: GSE4573), the FUBP1 mRNA level did not appear to be correlated with tumor stages." (PMID 32481602, 2020).
astrocytoma (10 papers, 2012 to 2024). "Thus, in our work, we analyzed neither LOH of 1p/19q nor the mutational status of CIC/FUBP1 in astrocytomas." (PMID 24810474, 2014).